TRAF3IP2 (TRAF3 interacting protein 2)
Diseases named in the same sentence as TRAF3IP2 in open-access papers (continued):
Sharing a sentence is not in itself a finding about the gene and the disease.
VKH syndrome (1 paper, 2014). "In this study, we show that TRAF5 and TRAF3IP2 gene polymorphisms are associated with VKH syndrome and ocular BD in a Han Chinese population." (PMID 24416204, 2014). "Taken together, our study, for the first time, provides evidence for a role of TRAF5 and TRAF3IP2 polymorphisms in the development of BD and VKH syndrome." (PMID 24416204, 2014). "Although our results suggested that TRAF5 and TRAF3IP2 are associated with the development of BD and VKH syndrome, it is still unknown how these SNPs exert their roles in these two diseases." (PMID 24416204, 2014). "Polymorphisms of the TRAF5 and TRAF3IP2 genes in VKH syndrome." (PMID 24416204, 2014). "This study provides evidence that TRAF5 and TRAF3IP2 genes are involved in the development of BD and VKH syndrome." (PMID 24416204, 2014).
tumor (13 papers, 2015 to 2025). "By depleting the energy reserves of TNBC cells and reactivating these critical stress response pathways, TRAF3IP2 silencing exerts a potent anti-tumor effect, evidenced by the substantial reduction in ATP production and tumor viability." (PMID 41436543, 2025). "KIRC tumor groups expressed higher levels of TRAF3IP2 than normal groups, according to the GEO database (GSE22316)." (PMID 35897085, 2022). "For the first time, our novel data show that TRAF3IP2 levels are significantly upregulated in highly vascularized areas in the GBM tumor microenvironment, including the tumor-infiltrating region." (PMID 36046049, 2022). "As an activator protein in the NF-κB and TNF (tumor necrosis factor), TRAF3IP2 is believed to play a clear role in tumor initiation and progression." (PMID 35897085, 2022). "The adaptor molecule TRAF3IP2 (TRAF3 Interacting Protein 2) is an upstream regulator of NF-κB, AP-1 and stress-activated kinases, and its sustained activation contributes to tumor progression." (PMID 32483202, 2020). "On the other hand, TRAF3IP2 overexpression in keratinocytes is shown to induce proliferation and tumor growth." (PMID 32483202, 2020). "Both tumor weight and tumor volume (Fig. 4DII) were significantly suppressed when Rab27a or TRAF3IP2 was silenced." (PMID 32483202, 2020). "Knockdown (KD) of Rab27a (MDAKDRab27a) or TRAF3IP2 (MDAKDTRAF3IP2) in triple negative MDA-MB231 cells reduced tumor growth by 70–97% compared to wild-type tumors (MDAw)." (PMID 32483202, 2020). "on the other hand, targeting TRAF3IP2 suppressed both tumor growth as well as macro- and micrometastasis." (PMID 32483202, 2020). "Correspondingly, the silence of TRAF3IP2 inhibited tumor growth in vivo." (PMID 35897085, 2022). "In addition to interact with IL-17 protein, TRAF3IP2 binds to the mRNA of IL-17 directly to promote inflammation in tumor cells." (PMID 35897085, 2022). "Since Rab27a and TRAF3IP2 contribute to exosome release and inflammation, respectively, we hypothesized that targeting Rab27a or TRAF3IP2 will reduce inflammation, tumor formation, growth and metastasis of BC in a preclinical breast xenograft model." (PMID 32483202, 2020). "Furthermore, targeting Rab27a or TRAF3IP2 each reduced the potential of the tumor cells with the surrounding stroma, indicated by reduced growth of MSCs coinjected with MDAKDRab27a." (PMID 32483202, 2020). "In addition to inhibiting tumor growth and metastasis, silencing TRAF3IP2 disrupted inter-cellular inflammatory mediator-mediated communication with mesenchymal stem cells (MSCs) injected into contralateral mammary gland, evidenced by the lack of tumor growth at MSC-injected site." (PMID 32483202, 2020). "Electron microscopic analysis indicated that silencing Rab27a results in the formation of a porous cell surface in MDAKDRab27a cells, while silencing TRAF3IP2 resulted in a rough surface, suggesting that Rab27a and TRAF3IP2 might be involved in remodeling or destabilization of tumor cell membrane." (PMID 32483202, 2020). "TRAF3IP2 − AS1, was related to ferroptosis, pyroptosis and N6-methyladenosine (m6A) and has utility in predicting PC prognosis, depicting the tumor immune microenvironment and guiding immunotherapy." (PMID 39987145, 2025). "The difference in TRAF3IP2 expression between normal brain and GBM is likely greater than the difference in TRAF3IP2 expression between various tumor tissues." (PMID 36046049, 2022). "In essence, our data indicate that TRAF3IP2 is a tumor-derived factor that is important for tumor progression in NONO-TFE3 tRCC, uncovering a new regulatory mechanism that drives tumor progression." (PMID 35897085, 2022). "Targeting TRAF3IP2, as a representative of the soluble fraction of the TME, however, suppresses tumor growth as well as macro- and micro-metastasis." (PMID 32483202, 2020).
tumor (continued). "Intriguingly, their respective antisense protein coding genes (HMGA2 for TROLL-2 and TRAF3IP2, also known as ACT1, for TROLL-3) are both known oncogenes supporting tumour growth and dissemination." (PMID 33056990, 2020). "Our data demonstrated that targeting TRAF3IP2 inhibits NF-κB activation and pro-inflammatory TME, possibly contributing to tumor regression." (PMID 30038719, 2018). "Additionally, TRAF3IP2 also contributes to stabilizing the mRNA of CXCL1, which is involved in the angiogenesis, inflammatory response, and tumor formation." (PMID 40455858, 2025). "Future studies will assess the efficacy of targeting TRAF3IP2 as a monotherapy or a combination therapy in robust animal models of heterogeneous primary GBM, with reductions in tumor size, angiogenesis, cerebral edema, and improvements in overall and disease-free survival as critical endpoints." (PMID 36046049, 2022). "Silencing TRAF3IP2 also blocked interaction between tumor cells and MSCs injected into the contralateral gland, as evidenced by the lack of tumor formation on MSCs injected site." (PMID 32483202, 2020). "In the present study, we found that overexpressed TRAF3IP2 in NONO-TFE3 tRCC could enhance tumor progression through function as a co-activator of NOTCH1 to mediate NOTCH1 target genes." (PMID 35897085, 2022). "Therefore, the observation that the tumor-infiltrating region of GBM has the highest expression of TRAF3IP2 is a statistically and translationally significant finding that points to TRAF3IP2 as a key driver of metastasis, which depends on angiogenesis at the infiltrating edge of the tumor." (PMID 36046049, 2022). "To delve further into one potential function of the HNRNPK in tumor progression of NONO-TFE3 tRCC, we constructed a dCas9-based system to recruit HNRNPK to the TRAF3IP2 promoter by MS2-loop on gRNA." (PMID 35897085, 2022).
infection (10 papers, 2012 to 2023). The state of being infected such as from the introduction of a foreign agent such as serum, vaccine, antigenic substance or organism. "An additional four genes were upregulated in ΔprgH STm infection and were involved in the regulation of glycolysis (PFKFB3) and cytokine signaling (SOCS3), and intracellular signaling (RASD1, TRAF3IP2)." (PMID 37854334, 2023). "Similar to WT STm infection, genes involved in the regulation of immune responses (ATF3, BATF3, ETS2, IRF9, NFκB2, MAFA, TNFAIP3), effector functions, (CCL4, CD200L, CD40, CD72, CD80, IL18) and TLR signaling, (EAF2, TLR15, TRAF3IP2, TOLLIP) were upregulated after ΔprgH STm infection in both models." (PMID 37854334, 2023).
cancer (9 papers, 2013 to 2025). A tumor composed of atypical neoplastic, often pleomorphic cells that invade other tissues. "This study aims to elucidate the potential link between TRAF3IP2 and metabolic regulation in cancer cells." (PMID 41436543, 2025). "5- Protein–Protein Interactions: Although we employed FK866 to corroborate our metabolic findings, additional protein–protein interaction studies are essential to fully elucidate the molecular mechanisms by which TRAF3IP2 controls metabolic activity in cancer cells." (PMID 41436543, 2025). "The specific biological function of TRAF3IP2 in some cancers is well-defined, but the actual mechanism of TRAF3IP2 in the intracellular component is still unknown." (PMID 35897085, 2022). "ASCs with TRAF3IP2 knockdown (ASCTRAF3IP2KD) did not exhibit changes in TRAF3IP2, NAMPT or SIRT1 levels, indicating a cancer-specific effect of TRAF3IP2 silencing." (PMID 41436543, 2025). "The results showed that TRAF3IP2 was highly expressed in NONO-TFE3 tRCC tissues and cells, and the silence of TRAF3IP2 inhibited the proliferation, migration, and invasion of UOK109 cells which were derived from cancer tissue of patient with NONO-TFE3 tRCC." (PMID 35897085, 2022).
connective tissue disorder (1 paper, 2023). A disease involving the connective tissue. "Indeed, mono- or biallelic deleterious variants of IL17F, IL17RA, IL17RC, and TRAF3IP2 (encoding ACT1) have been detected in patients with isolated CMC, and MAPK8 has been identified in patients with both CMC and a connective tissue disorder." (PMID 37577484, 2023).
TRAF3IP2 also shares sentences with these, for which no sentence is quoted: colitis (7 papers); asthma (4); Crohn disease (3); inflammatory bowel disease (3); Lymphadenopathy (3); lymphoma (3); thyroid cancer (3); acne (2); acute myocardial infarction (2); allergies (2); Arthritis (2); endothelial dysfunction (2); experimental autoimmune encephalomyelitis (2); glomerulonephritis (2); iron deficiency (2); nasal polyps (2); nephritis (2); osteoarthritis (2); periodontitis (2); peripheral T-cell lymphoma (2); rheumatoid arthritis (2); Splenomegaly (2); triple-negative breast carcinoma (2); ulcer (2); viral infection (2); acute lung injury (1); adenocarcinoma (1); adenoma (1); adult T-cell leukemia/lymphoma (1); allergic asthma (1).
A further 42 diseases each share a sentence with TRAF3IP2 in 1 paper.